ROR2 (ROR family WNT receptor 2)
Diseases named in the same sentence as ROR2 in open-access papers (continued):
Sharing a sentence is not in itself a finding about the gene and the disease.
cancer (continued). "We show that cytoneme-based Wnt transport operates in diverse processes, including zebrafish development, murine intestinal crypt and human cancer organoids, demonstrating that Wnt transport by cytonemes and its control via the Ror2 pathway is highly conserved in vertebrates." (PMID 30060804, 2018). "In the cancer cells, miR-124 might target ROR2-mediated Wnt signaling and B7-H3, a T cell co-stimulatory molecule, to produce its anti-tumor action, while it might target Synpo to produce its analgesic effect in the spinal cord." (PMID 28887457, 2017). "Interestingly, the combination of both, Ror2 overexpression and additional stimulation with its ligand Wnt5a (pRor2 + Wnt5a condition), was able to even further enhance cancer cell invasion compared to the Ror2 overexpression alone." (PMID 28695110, 2017). "A correlation between Wnt5a/Ror2 and pathological grade suggests that Wnt5a/Ror2 signaling pathway could play a role in the aggressiveness of this cancer, perhaps promoting the EMT and metastasis process." (PMID 28427201, 2017). "In recent years, the interaction between ROR2 and Wnt5A in cancer has received great attention." (PMID 28536612, 2016). "However, a constitutive expression or increased expression of Wnt5a and its receptor Ror2 is involved in enhanced invasive and metastatic properties of many cancer types, suggesting an oncogenic role of Wnt5a/Ror2 signaling in tumorigenesis." (PMID 27895670, 2016). "Taken together, these studies suggest that ROR2 exerts oncogenic activity and may be an ideal candidate as a prognostic biomarker and novel therapeutic target for some human cancers." (PMID 26305508, 2015). "PTK7 and Ror2 expression is frequently deregulated in a variety of cancers." (PMID 26680417, 2015). "The role of ROR2 and Wnt5a in cancer is complex, depending on the tumor type and molecular context." (PMID 26305508, 2015). "Thus, ROR2 mediates polarized cell migration, invasion, and tumor growth; however, the mechanism by which ROR2 functions to promote cancer remained elusive." (PMID 26328272, 2015). "RTK-like orphan receptor 2 (ROR2) is overexpressed in several cancers and has tumorigenic activity." (PMID 26259918, 2015). "Together, these findings suggest that Ror2 plays a central role in influencing the ccRCC phenotype, and can be considered as a negative prognostic biomarker and potential therapeutic target in this cancer." (PMID 25542006, 2014). "Otherwise, as recently reported in human cancers, Wnt5a/Ror2 signaling may up-regulate the expression of matrix metalloproteinases (MMPs) such as MMP1, MMP2, and MMP13 to increase cell invasiveness." (PMID 25211363, 2014). "We selected an established cancer cell line, which expresses low levels of Ror2 basally and is known to display a xenograft growth phenotype, anticipating that Ror2 expression might modify the tumorigenic phenotype rather than act overtly as an oncogene." (PMID 25542006, 2014). "Expression of Ror2 has been shown to mediate expression of several MMPs, which may contribute to cell migratory/invasive phenotypes in a multitude of cancers including RCC." (PMID 25542006, 2014). "Furthermore, high expression of Ror2 in ccRCC patients correlated with significant lower overall survival, cancer specific survival, and recurrence free survival." (PMID 25542006, 2014). "Moreover, our exploration of cell lines has demonstrated a wide range of Ror2 expression in cancer cell lines, with 786-0 RCC cells at the low end of the spectrum." (PMID 25542006, 2014). "In addition, an analysis of cancer specific survival in all ccRCC patients found that patients within the Ror2-Low subtype had significantly longer survival times (P = 0.0002)." (PMID 25542006, 2014).
cancer (continued). "Fzd7 inhibitors, monoclonal antibodies against ROR2, and small-molecule inhibitors of EV biogenesis or uptake are under active investigation in several cancers and may offer combinatory strategies with androgen deprivation and/or chemotherapy to mitigate EV-mediated pro-metastatic signalling." (PMID 41007281, 2025). "Additionally, it has relevance to various cancer types where ROR2 plays a role." (PMID 37832874, 2023). "Therefore, further studies on ROR2 function under the lens of its role in “phenotype switching” might contribute to a better understanding of cancer progression." (PMID 36127680, 2022). "However, caution should be exercised when using ROR2-based therapies since they might be detrimental in some contexts, such as in those cancers where ROR2 behaves more clearly like a tumor suppressor gene." (PMID 36127680, 2022). "In this article, we overview recent advances in our understanding of the roles of Ror1 and Ror2-mediated signaling in the development, tissue regeneration and age-related diseases, and discuss their potential to be therapeutic targets for chronic inflammatory diseases and cancers." (PMID 35493090, 2022). "As ROR2 and WNT5A functions are intimately associated--indeed, ROR2 knockout mice phenocopy most of alterations seen in WNT5A knockout mice --ROR2 and WNT5A might also have parallel or complementary roles in cancer." (PMID 20591152, 2010). "Based on our finding of increased ROR2 expression in HR cell lines, we investigated the therapeutic role of the YAP pathway in trastuzumab resistance in HER2-positive cancer cells." (PMID 40542295, 2025). "And we have identified some crucial LTA4H-bound genes that regulate cancer development, like NEAT1, LINC00657, LTBP3 and ROR2." (PMID 36923505, 2023). "Previous studies have reported the interaction between PTK7 and ROR2, FGFR1, or EGFR in cancer cells." (PMID 37569547, 2023). "We therefore concluded a stimulatory effect of EV-associated ROR1 and ROR2 on cancer cell invasion requiring the presence of RhoA without significantly upregulating its expression.We next analyzed whether EV uptake was required for the invasion-promoting effect of ROR-EVs." (PMID 37430307, 2023). "We will give a comprehensive overview about the downstream signaling elicited by ROR1 and ROR2, and revisit the current treatment strategies and first promising clinical data for targeting the WNT/ROR pathway in the context of cancer." (PMID 33445713, 2021). "Further, the effect of targeting ROR2 is being evaluated in phase 1 and 2 clinical trials (NCT03504488, NCT03393936, and NCT03960060) for patients with advanced cancer." (PMID 34774050, 2021). "As the OVCAR3 cell line expressed both ROR1 and ROR2, we were interested to investigate the synergistic effect of ROR1 and ROR2 on cancer cell behaviour." (PMID 26515598, 2015). "Mechanistically, MYOD1L122R transcriptionally activates Receptor tyrosine kinase-like Orphan Receptor 2 (ROR2) to turn on the non-canonical Wingless/Integrated (WNT) planar cell polarity pathway to increase both cancer stemness and therapy resistance." (PMID 42236477, 2026). "Utilizing existing drugs targeting ROR2 or components of the PI3K-Akt pathway could expedite translation into clinical trials, capitalizing on their established roles in MB and broader cancer contexts." (PMID 38632356, 2024). "For instance, the therapeutic relevance of targeting the non-canonical Wnt receptors ROR1 and ROR2 (receptor tyrosine kinase-like orphan receptor) has been investigated in numerous cancers of both hematological and epithelial origin." (PMID 37400436, 2023). "ROR2 is implicated in the WNT pathways and has been reported to drive both the canonical and non-canonical WNT pathways in cancer cells." (PMID 35246138, 2022). "Overexpressions of ROR1, ROR2, and PTK7 have been detected in numerous cancers." (PMID 35504983, 2022).
cancer (continued). "Experimental blocking of Tyrosine‐protein kinase transmembrane receptor (ROR2) receptors reversed the positive effect of WNT5A in cancer metastases and may induce dormancy in bone in a WNT5A/ROR2‐dependent manner." (PMID 33639039, 2021). "While the lack of the first, Ig-like extracellular domain, did not affect the invasion-promoting effect of ROR2, a trend (p = 0.08) for reduced cancer cell invasiveness was observed when overexpressing ROR2 lacking the CRD." (PMID 34911552, 2021). "Thus, using PROTACs, we are able to expand the druggable space to a class of proteins with immense cancer relevance (HER3, ROR2, etc.)." (PMID 33568647, 2021). "Obviously, the notion of WNT5A as the sole ligand for human ROR2 no longer holds true which opens novel insights in the regulation of non-canonical WNT signaling in cancer." (PMID 34911552, 2021). "ROR2, one of the ROR RTKs, has been brought into focus in cancer field during the past decades." (PMID 31878941, 2019). "The expression of CTHRC1 and the positive correlation between Wnt5a/Ror2 and pathological grade suggests that the Wnt5a/PCP signaling pathway could play a role in the aggressiveness of this cancer." (PMID 28427201, 2017). "Cancer cells may express ROR1 or ROR2 at levels not observed in normal post-partem tissues and, therefore, the protein antigens encoded by these genes could serve as potential targets for therapy." (PMID 37029329, 2023). "A conditionally active biologic (CAB)-ROR2- antibody drug conjugate (ADC) named BA3021 was developed to selectively bind to ROR2 in the context of tumour microenvironment and has been reported to inhibit growth of ROR2 positive cell lines and xenografts of several cancers." (PMID 34763666, 2021). "Treatment of ROR2-overexpressing cells with soluble WNT ligand antagonists such as sFRP1 or DKK1 as well as an inhibitor blocking non-canonical WNT-JNK signaling inhibited ROR2-induced cancer cell invasiveness." (PMID 34911552, 2021). "In contrast, ROR2 may play a more direct role in triggering the noncanonical Wnt signalling pathway in noncanonical signalling driven cancers." (PMID 32807831, 2020). "In addition, our data showed that patients with double positive cancers (ROR2+/Wnt5a+) had significantly worse survival than those with double negative cancers (ROR2-/Wnt5a-)." (PMID 26305508, 2015). "The minor difference may be from the choice of cutoff point; these data all support the finding that ROR2 expression was higher in cancer tissues than in non-tumor tissues." (PMID 26259918, 2015). "This showed that the ROR2 promoter was completely unmethylated in non-tumourigenic colon primary tissues and in vitro-growing colonocytes, whilst it was densely hypermethylated in most cancer cell lines analysed (HT29, HCT15, DLD1, COLO205 and RKO)." (PMID 20591152, 2010). "ROR2/WNT5A upregulation could be advantageous to cancers driven by non-canonical Wnt signalling, while their epigenetic downregulation would benefit tumours, such as colon and haematopoietic cancers, that are driven by canonical Wnt signalling." (PMID 20591152, 2010). "Unlike single-cancer studies, we uncovered FZD2’s context-dependent functions in both canonical Wnt activation (e.g., Wnt3A/ROR2 axis) and immune evasion mechanisms (e.g., M2 macrophage recruitment)." (PMID 40444048, 2025).
tumor (90 papers, 2008 to 2026). "Targeting ROR2 with antibody-drug conjugates kills MYOD1L122R-mutated tumor cells, offering therapeutic opportunities." (PMID 42236477, 2026). "The high tumorigenicity of this cell line is also associated with the overexpression of several tumor markers, including ROR2 and FGFR, and it showed sensitivity to irreversible pan-ErbB inhibitors and DNA alkylating agents." (PMID 38565739, 2024). "This study explores the sequence, sub-cellular localisation and expression of various transcript variants of ROR1 and ROR2 in healthy human tissues and tumour samples." (PMID 36289823, 2022). "ROR1 and ROR2 transcript variant expression was analysed in 33 different tumour types profiled by TCGA." (PMID 36289823, 2022). "High levels of ROR2 were furthermore associated with defects in cell morphology and cell-cell-contacts leading to increased tumor invasiveness." (PMID 34911552, 2021). "In mice, ROR2-positive tumors are associated with accelerated tumor growth and a shorter survival time, confirming the tumor-promoting role of ROR2 in vivo." (PMID 34911552, 2021). "Several studies indicate an association of Ror2, in some cases downstream of Wnt5a, with tumor invasiveness and metastasis." (PMID 26680417, 2015). "The Kaplan–Meier method and Cox regression analyses showed that high ROR2 expression in tumor cytoplasm or stromal cells was significantly associated with malignant attributes and reduced survival in PDAC." (PMID 26259918, 2015). "ROR2 has clearly been linked to aggressive disease patterns and has been implicated in important tumor promoting signaling pathways constituting an promising target." (PMID 26328272, 2015). "Prior work had shown that knockdown of Ror2 in RCC cells resulted in significant loss of tumor growth in xenografts." (PMID 25542006, 2014). "Because earlier work has shown that Ror2 expression is associated with tumor growth phenotypes in ccRCC cells, we sought to expand our understanding of the tumor promoting role of Ror2 in ccRCC." (PMID 25542006, 2014). "The relationship between ROR2 expression and tumor differentiation was shown in both clinical specimens and cell lines, in which decreased expression of ROR2 was associated with decreased tumor differentiation." (PMID 37814183, 2024). "In addition, high stromal ROR2 expression was significantly associated with lymph node invasion and tumor stage in this study." (PMID 37722040, 2023). "Considering that ROR2-lEVs showed the highest increase in tumor patients compared to controls and provided the best separation between both groups in ROC analyses, an association with the tumor disease seems likely." (PMID 37430307, 2023). "Based on these findings, we hypothesized that deletion of GCTB-OCs by denosumab might decrease the level of sFRP in tumor tissues, activate a cascade of Wnt-5a/Ror2/Rac1 signaling, and finally cause the osteoblastic differentiation of GCTB-SCs." (PMID 35927428, 2022). "However, the increased ROR2 expression was positively associated with the tumor diameter (P = 0.032)." (PMID 32614787, 2020). "However, ambivalent research conclusions of ROR2 make its role in tumor confused and the underlying mechanism is far from being understood." (PMID 31878941, 2019). "Our study therefore suggests that ROR2 expression in the tumor microenvironment may be associated with the invasive activity of PDAC tumor cells." (PMID 26259918, 2015). "Although ROR2 is dynamically regulated during early embryonic development and exhibits a gradual decline in expression from midgestation onwards, its re-expression or residual presence is associated with aggressive tumor features and poor prognosis in a wide spectrum of malignancies." (PMID 38632356, 2024). "Ror2 may be serving purely as a scaffolding protein or allosteric regulator, whereby these mutations may be interfering with its effective binding and regulation by other intracellular signaling partners mediating these tumor phenotypes." (PMID 25542006, 2014).
tumor (continued). "In many contexts, including the primary tumour setting investigated in this study, the Wnt5a/ROR2 axis is a potent driver of EMT, cytoskeletal rearrangement, and invasion." (PMID 41007281, 2025). "ROR2 exhibits tumor suppressor activity in colon cancer and hepatocellular carcinoma driven by canonical Wnt signaling." (PMID 41470892, 2025). "Ozuriftamab vedotin’s CAB design allows it to selectively and reversibly bind ROR2 under the acidic conditions of the tumor microenvironment, minimizing off-target binding in normal tissues." (PMID 41375018, 2025). "Ozuriftamab vedotin is an ADC designed to bind to ROR2 under low pH conditions of the tumor microenvironment, thus reducing off-target toxicity by sparing normal tissue and improving pharmacokinetics." (PMID 41018114, 2025). "On average, CTNNB1 mutated tumors showed 33.3% of ROR2 positive cells, while only 13.3% of WT tumor cells showed ROR2 positivity." (PMID 41227323, 2025). "Among the Wnt-related genes relevant to PCa, Wnt3a, Wnt5a, Fzd7, sFRP1, and ROR2 stand out due to their roles in modulating tumour behaviour under hypoxic conditions." (PMID 41007281, 2025). "Subsequently, silencing ROR2 expression promoted apoptosis and inhibited proliferation, migration, and invasion of MB cells in vitro and decelerated MB tumor growth in vivo." (PMID 38632356, 2024). "These combined observations strongly emphasize ROR2’s role as a tumor promotor in all four MB subgroups." (PMID 38632356, 2024). "To further explore the relationship between ROR2 expression and tumor differentiation, we examined clinical samples." (PMID 37814183, 2024). "This study presents the downregulation of miR-124-3p and miR-194-5p in pediatric MB and their role as tumor suppressors through their synergistic upregulation of ROR2." (PMID 38632356, 2024). "Our findings indicate that miR-124-3p and miR-194-5p function as tumor suppressors, inhibiting MB progression via the ROR2/PI3K/Akt axis, suggesting a key mechanism and therapeutic targets for MB patients." (PMID 38632356, 2024). "Central to this paradigm is ROR2, a pleiotropic transmembrane receptor protein with putative kinase activity, which exerts pivotal roles in the pathogenesis of various tumor types." (PMID 38632356, 2024). "As further support, in our immunohistochemical staining of ROR2 in 243 HCC cases, ROR2 negativity was significantly associated with high level of AFP (P = 0.006) and poor differentiation (P = 0.015), which correlated with tumor differentiation." (PMID 37814183, 2024). "To elucidate the in vivo roles of miR-124-3p, miR-194-5p, and ROR2, we established tumor xenograft models using nude mice." (PMID 38632356, 2024). "This study demonstrated that ROR2 negativity determined by immunohistochemical staining was significantly associated with high AFP and low tumor differentiation in HCC." (PMID 37814183, 2024). "Taken together, our results provide evidence of an intercellular transport mechanism for membrane-spanning proteins in the tumor microenvironment: The cognate WNT5A coreceptor ROR2 can be transported from CAFs to receiving tumor cells on signaling filopodia." (PMID 37722040, 2023). "We further demonstrate that the transferred receptor ROR2 remains active in the tumor cells to influence cell polarization and migration." (PMID 37722040, 2023). "Upregulated ROR2 and Wnt5a have shown to represent poor tumor stage and lymphatic metastasis in LSCC, suggesting that ROR2 was an independent prognostic factor." (PMID 36923505, 2023). "In genetically engineered mouse models of TNBC, Wnt/Ror2 signaling also regulates tumor cell-intrinsic collagen production and fibronectin/integrin signaling to modulate tumor cell dissemiation." (PMID 37440925, 2023). "On one side, ROR2 expression would slow down tumor growth but on the other hand, it would favor an invasive phenotype that facilitates metastasis." (PMID 36127680, 2022).